CTLA4 (cytotoxic T-lymphocyte associated protein 4)
Diseases named in the same sentence as CTLA4 in open-access papers (continued):
Sharing a sentence is not in itself a finding about the gene and the disease.
Hepatitis (continued). "The incidence of ICI-derived hepatitis is approximately 1-3% for programmed cell death 1 (PD1) inhibitors and 3-9% in cytotoxic T-lymphocyte-associated protein 4 (CTLA4) inhibitors." (PMID 37205101, 2023). "Anti-CTLA-4 inhibitor-containing regimen was also significantly associated with severity; 13 patients under such regimen developed CTCAE grade 4 hepatitis (13/45 vs. 9/71 for non-CTLA-4-treated patients, p <0.001)." (PMID 37138674, 2023). "Hepatic histologic findings of checkpoint-inhibitor-induced hepatitis are sparse in the literature and vary depending on the type of checkpoint inhibitor (PD-1, PD-Ligand 1 or anti-cytotoxic T-lymphocyte antigen 4 (CTLA-4))." (PMID 37510756, 2023). "The time until the first onset of hepatitis was 8–16 weeks with anti-PD-1/PD-L1 antibodies, 8–9 weeks with anti-CTLA-4 antibodies, and 6–9 weeks when used in combination." (PMID 38137632, 2023). "These mice develop hepatitis, characterized by mononuclear cell infiltration to the periportal and pericentral hepatic veins, after receiving anti-PD-1 and anti-CTLA-4." (PMID 37631034, 2023). "Data from liver biopsies, interestingly, show that anti-PD-1 hepatitis, anti-CTLA-4 hepatotoxicity, and AIH present distinct histological findings." (PMID 35945730, 2022). "Younger age more accurately predicts ICB-hepatitis after anti-PD-1&anti-CTLA4 checkpoint therapy at baseline compared to herpes virus serology or TEM subsets." (PMID 36503532, 2022). "Tremelimumab, a monoclonal anti-CTLA4 antibody was assessed in a phase II multi-center clinical trial including 20 patients with advanced HCC from hepatitis C viral etiology." (PMID 33672017, 2021). "Although the histological responses to PD-1/PD-L1 mAbs are diverse, there is a lower incidence of liver irAEs to anti-PD-1/PD-L1 agents than anti-CTLA-4 mAbs, and few records of PD-1/PD-L1 inhibitor-induced hepatitis are available." (PMID 32507925, 2020). "In this review, we summarize recent literature relating to PD-1, CTLA-4, and other inhibitory receptors in antigen-specific T cell exhaustion in viral hepatitis, including hepatitis A, B, C, and others." (PMID 28703774, 2017). "The PD-1 and CTLA-4 expressions during the symptomatic phase of acute hepatitis A seems to be dramatically reduced when patients are in recovery." (PMID 28703774, 2017). "Interestingly, CTLA-4 immunotherapeutic agents used in advanced cancer such as the anti-CTLA-4 monoclonal antibody ipilimumab, which augments T-cell activation and proliferation, have been associated with immune-mediated multi-organ damage, including several cases of hepatitis and liver failure." (PMID 27187363, 2016). "These “humanized” mice treated with anti-CTLA-4 antibodies develop hepatitis, adrenalitis, and sialitis, as well as anti-nuclear antibodies (IgM or IgG)." (PMID 26337719, 2015). "Additionally, hepatitis and pancreatitis as irAEs are more frequent with combination therapies involving PD-1 inhibitors and CTLA-4 inhibitors." (PMID 40423705, 2025). "Hepatitis was more prevalent in patients treated with anti-CTLA-4/PD-1 combination therapy." (PMID 39135626, 2024). "However, IL-1β secretion is regulated by CTLA4-Ig fusion protein, and the administration of IL-1β inhibitors in a mouse model of hepatitis upregulates the expression of PD-1 and CTLA4 in the liver." (PMID 38580797, 2024). "The combination of α-PD1/CTLA4 increases the rate of hepatitis." (PMID 37205101, 2023). "Reducing the incidence hepatitis by opting for αPD-1 monotherapy hints that CTLA-4 blockade may be mechanistically important for development of hepatitis in CD4+ TEM≥21% patients." (PMID 33664251, 2021). "In addition, hepatitis is higher in patients who were treated with combination therapy (14–18%) than patients who were treated with anti-CTLA4 (4–9%) or anti-PD1 (1–4%) monotherapy." (PMID 32580338, 2020).
Hepatitis (continued). "Furthermore, AYAs more often developed a grade 3–4 hepatitis following anti-PD-1 and anti-CTLA-4 combination treatment when compared to older adults (9 out of 21 versus 36 out of 169, p = 0.03)." (PMID 32726988, 2020). "However, rechallenge with an anti–PD-1 antibody in 4 patients out of 21 with previous liver toxicity under anti–CTLA-4 and anti–PD-1 combination therapy did not cause a recurrence of hepatitis." (PMID 35126126, 2021). "Because anti-CTLA-4 inhibitor is associated with hepatitis, specific predictors of irSC factors could not be detected in this study." (PMID 34046801, 2021). "PubMed/MEDLINE, EMBASE, and CENTRAL databases were searched in July 2023 based on keywords including ICIs (anti–Programmed cell death protein 1/Programmed Death-Ligand 1, anti–CTLA–4, and anti-LAG3) and hepatitis." (PMID 39298568, 2024). "Furthermore, hepatitis, an important irAE, was significantly decreased in the JX-594 and PD-1 inhibitor combination group, suggesting that the JX-594 and PD-1 inhibitor has potential benefits for reducing ICI-induced toxicity, especially that caused by the CTLA-4 inhibitor." (PMID 38291394, 2024). "used combined blockade of PD‐1, CTLA‐4, and IDO1 to establish a mouse model of ICI‐induced hepatitis and studied the immune mechanism in this model." (PMID 39001676, 2024). "The incidence of hepatitis in patients treated with anti-PD-1 ICI is approximately 5%, but this rises to 30% in patients treated with a combination of CTLA-4 and PD-1 blockers." (PMID 37631034, 2023). "Therapeutics targeting CTLA-4 or PD-1/PD-L1 have achieved obvious outcomes in advanced HCC, but they are limited when used in combination because of immune-related adverse events, such as hepatitis." (PMID 38973608, 2024). "Hepatitis occurs in 5–10% of patients during treatment with ICI as a monotherapy (~2% grade 3) and 25–30% during treatment with a combination of anti-PD(L)-1 and anti-CTLA-4 (~15% grade 3)." (PMID 39064558, 2024). "In this study, we review the current understanding of immune inhibitory receptors such as PD-1, CTLA-4, CD244, Lymphocyte activation gene 3 (LAG-3), T cell immunoglobulin domain and mucin domain-3 (Tim-3), and CD160 (expressed on virus-specific T cells in hepatitis)." (PMID 28703774, 2017).
cutaneous melanoma (79 papers, 2013 to 2025). A primary melanoma arising from atypical melanocytes in the skin. "We retrospectively identified patients with advanced cutaneous melanoma who received first-line anti-programmed cell death protein 1 (PD-1) with or without anti-cytotoxic T-lymphocyte associated protein 4 (anti-CTLA-4) from 10 hospitals in the Netherlands." (PMID 39045171, 2024). "High YY1 expression associated with a worse outcome of therapy with anti-CTLA-4 in skin melanoma (Van Allen), but was related to better anti-PD-L1 therapy outcomes in metastatic urinary bladder cancer (Mariathasan)." (PMID 37894300, 2023). "Recent data suggest that clinical benefit to immune checkpoint blockade therapy (e.g., anti-CTLA4) in cutaneous melanoma is associated with higher mutational burden." (PMID 28594900, 2017). "Ipilimumab is a monoclonal cytotoxic T-lymphocyte-associated protein 4 antibody that has demonstrated improved survival in cutaneous melanoma." (PMID 30363303, 2016). "Immunotherapy such as anti-PD1 (programmed cell death protein 1) anti-PD-L1 (programmed cell death protein—ligand 1) or CTLA-4 (cytotoxic T-lymphocyte-associated protein 4) therapy is often applied successfully in cutaneous melanoma, but has limited success in UM." (PMID 32998469, 2020). "In recent years, immunotherapy have gained attention due to favourable results obtained with immunological checkpoint inhibitors targeting cytotoxic T lymphocyte- associated antigen 4 (CTLA-4), ipilimumab and programmed cell death-1 (PD-1) pembrolizumab, in the management of cutaneous melanoma." (PMID 31109147, 2019). "Subsequent analysis of scRNA‐seq data from patients with skin cutaneous melanoma (SKCM) treated with a combination of PD‐1 and cytotoxic T‐lymphocyte‐associated protein 4 (CTLA‐4) mAbs revealed exclusive expression of NUPR1 in macrophages." (PMID 40305758, 2025). "This stands in contrast to cutaneous melanoma, where PD-1 inhibitors alone are highly effective and combined CTLA-4/PD-1 blockade further improves response and survival." (PMID 41228313, 2025). "Recent advances in immune checkpoint inhibition (ICI), particularly targeting PD-1 and CTLA-4, have significantly improved outcomes in cutaneous melanoma." (PMID 40683913, 2025). "A large analysis exploring the efficacy of ICIs in MM compared to cutaneous melanoma showed that nivolumab (anti-PD-1) combined with ipilimumab (anti-CTLA-4) had a greater efficacy than either agent alone for both diseases." (PMID 38275835, 2024). "Recently, targeted therapies, including inhibitors of c-KIT, NRAS/MEK or BRAF, and immunotherapies, including anti-CTLA-4 and anti-PD-1/PD-L1 antibodies, have revolutionized the treatment of cutaneous melanoma." (PMID 38326751, 2024). "In general, ALM seems to respond to anti-PD1 therapy, more specifically with combination therapy regimens, typically including anti-PD1 therapy with anti-CTLA4 therapy but at a lower frequency than when used for cutaneous melanomas." (PMID 38390259, 2024). "In 2011, the Food and Drug Administration (FDA) authorized the first immune checkpoint inhibitor, ipilimumab (anti-CTLA-4), for the treatment of metastatic or incurable cutaneous melanoma." (PMID 38254833, 2024). "In skin cutaneous melanoma, for both anti‐PD‐1 (Pembrolizumab) and anti‐CTLA‐4 (Ipilimumab), we see responders having higher IP expression pretreatment." (PMID 37097039, 2023). "PD-1 inhibitor monotherapy, or in combination with lymphocyte activation gene-3 inhibitor (relatlimab) or CTLA-4 inhibitors is the standard of care for advanced cutaneous melanoma." (PMID 36980308, 2023). "The era of immune checkpoint blockade (ICB) with nivolumab and pembrolizumab (anti-PD-1) alone or in combination with ipilimumab (anti-CTLA-4) has led to significant survival benefits in patients with cutaneous melanoma (CM)." (PMID 35158786, 2022).
cutaneous melanoma (continued). "Then, we employed the submap algorithm to classify sample responsiveness to PD-1 and CTLA4 inhibitors, with reference to a cohort of cutaneous melanomas treated with ICI inhibitors." (PMID 36177003, 2022). "The era of immune checkpoint blockade (ICB) with nivolumab and pembrolizumab (anti-PD-1) alone or in combination with ipilimumab (anti-CTLA-4) has led to prolonged survival in patients with cutaneous melanoma (CM)." (PMID 35158786, 2022). "Different drugs are used in immunotherapy for cutaneous melanoma, but the focus still remains on two groups, i.e., anti-PD-1 antibodies (nivolumab and pembrolizumab) and anti-CTLA-4 antibodies (ipilimumab)." (PMID 36291906, 2022). "It has shown extraordinary progress in patients with cutaneous melanoma, including PD-L1 and anti-cytotoxic T-lymphocyte antigen-4 (CTLA-4) checkpoint inhibitors." (PMID 34513843, 2021). "Last but not least, ALDH2 had the best prediction efficacy in assessing immunotherapeutic response compared with PD-L1, PD-1, CTLA4, CD8, and tumor mutation burden (TMB) in cutaneous melanoma." (PMID 35096916, 2021). "Antibodies targeting CTLA-4 and PD-1 in the treatment of cutaneous melanoma (CM) significantly improved treatment outcomes in metastatic CM." (PMID 34439182, 2021). "Among the inhibitory checkpoints, cytotoxic T-lymphocyte-associated protein 4 (CTLA-4) and programmed cell death protein 1 (PD-1) are the most studied and are promising targets for cutaneous melanoma treatment." (PMID 34572799, 2021). "During recent years immunotherapy for the treatment of cutaneous malignant melanoma has been a success story with antibodies against CTLA-4 and PD-1 paving the way for a new era of immune checkpoint inhibitors." (PMID 33344043, 2020). "Previous research in cutaneous melanoma showed that the combination of anti-CTLA-4 monoclonal antibodies and anti-PD-1 monoclonal antibodies was more effective but more toxic than single-agent therapy." (PMID 33344255, 2020). "In cutaneous melanoma, immune checkpoint inhibitors anti-CTLA4 and anti-PD1 and targeted therapies against BRAF and MEK have increased the overall survival." (PMID 33585548, 2020). "In light of this data, it is not surprising that recent studies in uveal melanoma have focused on the therapeutic effect of PD-1 inhibitors given their greater efficacy and more acceptable toxicity profile compared to CTLA-4 inhibitors in cutaneous melanoma." (PMID 30699934, 2019). "In cutaneous melanoma, the use of adjuvant CTLA-4 inhibitors and PD-1 inhibitors has been proven efficacious for locally advanced disease." (PMID 30699934, 2019). "Survival in metastasized cutaneous melanoma (CM) has been improved with the advent of inhibitors of immune checkpoints CTLA4 and PD‐1." (PMID 30993893, 2019). "In this study, we demonstrate that CTLA-4 is constitutively expressed in a large portion of patient-derived cutaneous melanoma cells, as well as tissues, and it is recognized by Ipilimumab." (PMID 23634660, 2013). "The results of our analysis demonstrated that the G199R mutation found in TCGA-DA-A1HV and SP82900 samples, which might be highly relative to cutaneous melanoma, exhibited the highest frequency within the CTLA-4 cytoplasmic domain." (PMID 38542966, 2024). "In addition, CYThigh skin melanoma patients who received anti-CTLA-4 and/or anti-PD-1 therapy had better clinical results due to a higher immunophenoscore, compared to those with low CYT levels." (PMID 38612436, 2024). "Furthermore, in skin melanoma patients being treated with anti-CTLA4 mab (Ipilimumab), it was shown that the intratumoral immune cytolytic levels increased the infiltration of CD8+ T cells and the expression of MHC class I molecules." (PMID 38612436, 2024). "Nonetheless, as MM is seemingly less responsive to immunotherapy than cutaneous melanoma, patients with resectable MM may need addition of anti-CTLA4 to anti-PD1 to derive clinical benefit." (PMID 36324592, 2022).
cutaneous melanoma (continued). "The importance of NK cells in this setting is indirectly confirmed by the fact that ipilimumab (anti-CTLA-4 monoclonal antibody) treatment depletes regulatory T cells in cancer patients, and is reported to improve NK cells’ functions in advanced cutaneous melanoma patients." (PMID 36613701, 2022). "Finally, it has also been demonstrated that macrophages, in hypoxic tumor regions, express the ligands of inhibitory PD-1 and CTLA-4, which are already found themselves overexpressed in the malignant cutaneous melanoma and participate in tumor escape." (PMID 33747916, 2021). "Indeed, low dose anti-CTLA4 (1 mg/kg) with full dose anti-PD1—either 3 mg/kg or 2 mg/kg has been investigated for the treatment of cutaneous melanoma in Checkmate-511 or KEYNOTE-029." (PMID 34298857, 2021). "A treatment for metastases is eagerly awaited: many different studies have tested anti-PD-1 and anti-CTLA-4 therapies in UM patients, but results have been unsatisfactory, especially in comparison with metastasized cutaneous melanoma, with very few complete or partial responses." (PMID 34503258, 2021). "For instance, checkpoint inhibitor (PD-1/ PD-L1 or CTLA-4) immunotherapies are emerging as a promising treatment in cutaneous melanoma; ipilimumab, an effective CTLA-4 inhibitor, has been FDA approved as treatment in metastatic cutaneous melanoma, yet it has dismal success rates of 0–5% in UM." (PMID 34789240, 2021). "Finally, the efficacy of immunotherapies combining anti-PD1 and anti-CTLA4 remains lower in mucosal melanomas compared to cutaneous melanoma." (PMID 32344828, 2020). "Cutaneous melanoma, a fatal and aggressive tumor, has witnessed a transformative shift in its clinical management over the past decade with the advent of anti-programmed cell death 1 (PD1) and anti-cytotoxic-T-lymphocyte-associated antigen 4 (CTLA-4) immunotherapies, as well as targeted therapies." (PMID 38539531, 2024). "In addition, immune checkpoint inhibitors, such as programmed cell death 1 (PD-1) and cytotoxic T lymphocyte antigen-4 (CTLA-4) inhibitors, have been successfully used in advanced cutaneous melanoma and may be effective against CM." (PMID 36059617, 2022). "Besides CTLA-4 blockade by ipilimumab, targeting new immune checkpoint inhibitory receptors and ligands such as programmed cell death 1 (PD-1) and programmed cell death ligand 1 (PD-L1) have evolved as further important targets in cutaneous melanoma." (PMID 25761109, 2015). "For the survival analyses, we included patients with a cutaneous melanoma or MUP treated with anti-PD1, anti-CTLA4/PD1, and BRAF/MEKi (n = 101)." (PMID 38473216, 2024). "The majority were cutaneous melanomas (90.9%) and the relapses were most commonly preceded by adjuvant anti-PD1 (76.2%), anti-CTLA4 (11.8%), or BRAF/MEKi (7%)." (PMID 38473216, 2024). "When specifically studying skin cutaneous melanoma (SKCM), we observed similar effects for anti-PD1 (HR: 0.65, FDR: 50%, p = 0.0072) and anti-CTLA4 (HR: 0.35, FDR: 1%, p = 4.1 × 10−5)." (PMID 38612803, 2024). "In analogy to the use in cutaneous melanoma (CM), ICB includes the antibodies anti-CTLA-4 (ipilimumab), anti-PD-1 (nivolumab, pembrolizumab), and the combination of anti-PD-1 with anti-CTLA-4 (dual ICB)." (PMID 34283061, 2021). "Our findings also corroborate that immunotherapies with PD-1 and/or CTLA-4 blockade, should be able to overcome resistance and broaden the clinical benefit, especially for CYT-high skin melanoma patients." (PMID 33779796, 2021). "Farshidfar and colleagues identified that acral melanomas have a lower overall immune cell infiltrate as compared to traditional cutaneous melanoma, but of these infiltrates, PD-1, LAG-3, CTLA-4, VISTA, TIGIT, and ADORA2 were highly expressed, introducing new possible therapeutic targets." (PMID 39001457, 2024).
cutaneous melanoma (continued). "The response to anti-PD-1 and anti-CTLA-4 ICT in wild-type (WT) and CXCR3KO mice has been evaluated using the Ret transgenic mouse model, a skin malignant melanoma model that is characterized by the overexpression of the human Ret transgene in melanin-expressing cells." (PMID 39474427, 2024). "This study found that negative correlations of CRABP2 and immune checkpoint markers (PD-1, PD-L1, and CTLA-4) were observed in breast invasive carcinoma (BRCA), skin cutaneous melanoma (SKCM), stomach adenocarcinoma (STAD) and testicular germ cell tumors (TGCT)." (PMID 38186580, 2023). "While cutaneous melanoma patients have response rate of 58% and 44% to combination anti-PD1 and anti-CTLA4 or anti-PD1 monotherapy, respectively, MM patients have response rates of 37-43% and 30% to combination anti-PD1 and anti-CTLA4 and anti-PD1 monotherapy, respectively." (PMID 36324592, 2022). "We also show that, apart from CTLA-4 and PD-1, there are many other immune receptors expressed by T-cells, which influence the TME and act as checkpoints, negatively regulating immune responses in skin melanoma." (PMID 36389735, 2022). "Systemic therapy approaches include the same treatments that have a demonstrated efficacy in cutaneous melanoma, including anti-programmed cell death protein 1 (anti-PD1) and anti-cytotoxic T-lymphocyte antigen-4 (anti-CTLA4) immune checkpoint inhibitors (ICI)." (PMID 34298857, 2021). "Immunotherapy is highly effective in cutaneous melanoma but yields only poor results in the treatment of UM: anti-PD-1 and anti-CTLA-4 blocking antibodies did not meet the expectations except for isolated cases." (PMID 33922591, 2021). "However, given the published data to date, overall activity of anti-CTLA-4 and anti-PD-1/PD-L1 agents in advanced uveal melanoma is limited and should not be used in frontline treatment as it stands in cutaneous melanoma." (PMID 31109147, 2019). "However, the already well-established PD-1 or CTLA-4 inhibitors in cutaneous melanoma are not nearly as successful in uveal melanoma." (PMID 31344957, 2019).